RNU6-354P (RNA, U6 small nuclear 354, pseudogene)
Gene: Small nuclear RNA gene on chromosome 15 (43,734,179 to 43,734,285, reverse strand). Ensembl gene ENSG00000206589.
Homologues: Orthologues: chimpanzee U6 (100% identical), macaque U6 (93% identical), guinea pig U6 (81% identical), rabbit U6 (79% identical), mouse Gm55901 (77% identical). Paralogues in human: RNU6-610P (100% identical), RNU6-45P (92% identical), RNU6-12P (91% identical), RNU6-13P (91% identical), RNU6-21P (91% identical), RNU6-26P (91% identical), RNU6-31P (91% identical), RNU6-32P (91% identical), RNU6-949P (91% identical), RNU6-1 (90% identical), RNU6-15P (90% identical), RNU6-17P (90% identical), and 1286 more.